AIF1 (allograft inflammatory factor 1)
Diseases named in the same sentence as AIF1 in open-access papers (continued):
Sharing a sentence is not in itself a finding about the gene and the disease.
infection (continued). "Similarly, Defensin and AIF1 were also down regulated by infection and HVL significantly augmented this inhibition." (PMID 23721325, 2013). "Inactivation of AIF1 might increase genomic plasticity of C. neoformans during infection and promote the generation of phenotypic adaptations such as new virulence traits and antifungal drug resistance." (PMID 22114551, 2011). "We also assessed the role of IL6, a lymphokine associated with CSFV infection, and presented a mechanistic hypothesis that CSFV Shimen up-regulate AIF1 expression to induce up-expressed IL6, to help us understand AIF1-related inflammation in CSFV Shimen infection." (PMID 32110485, 2020). "Although research on AIF1 has gradually increased, the role of this factor in the face of viral infections is little studied, and the mechanism underlying its role in CSFV Shimen strain infection remains unclear." (PMID 32110485, 2020). "Even though we are focusing on the early response (8, 24 and 48 hpi) during the infection, the genes expressed differentially at day 21, include CCL5, CCR5, TGFB3 and AIF1, and provide additional gene profiling data during the chronic infection stage." (PMID 18811943, 2008). "Notably, we found that the expression of specific markers of M1 type microglia (Aif1, Cd86, Cd40, Ccl2, Ccr2, Cx3cr1, IL-1β, IL-6, and NOS2) was elevated post infection." (PMID 36618398, 2022). "Western blotting analysis revealed differences in AIF1 and IL6 protein expression levels between CSFV-infected and uninfected control cells, which demonstrated that AIF1 and IL6 levels increased significantly in the first 48 h after infection relative to the levels at the 0 time point." (PMID 32110485, 2020). "Treatment with 100 mg/kg/day of FLC had antifungal activity against H99 and aif1 strains (but did not clear infection in the brains of the animals) and doubled the survival time of mice infected with FLCR strains." (PMID 22114551, 2011). "However, no study has assessed the role of AIF1 in monocyte-to-macrophage conversion, nor whether a pathogen can exploit the gene to perturb differentiation of myeloid subsets during infections." (PMID 33441583, 2021).
cancer (50 papers, 2010 to 2026). A tumor composed of atypical neoplastic, often pleomorphic cells that invade other tissues. "In our analysis, we first analyzed the expression and gene mutation patterns of AIF-1 across cancers by integrating multiple databases." (PMID 37014322, 2023). "This enabled them to determine which cancer hallmarks were enriched in the low- or high-AIF-1 subgroups, providing insight into the molecular mechanisms underlying cancer development and progression." (PMID 37014322, 2023). "The findings of the OS and DSS analyses were extremely consistent, indicating that AIF-1 is significantly connected with cancer patient prognosis and that AIF-1 is a risk factor for LGG and UVM and a protective factor for CESC, SKCM, and THCA." (PMID 37014322, 2023). "The results from OS and DSS analyses were highly consistent, showing that AIF-1 is significantly associated with the prognosis of cancer patients, and AIF-1 is a risk factor for LGG and UVM and a protective factor for CESC, SKCM, and THCA." (PMID 37014322, 2023). "Correlation analysis between AIF-1 and immune regulators in various cancers revealed a positive association between AIF-1 expression and numerous immune regulator genes in most tumors, except for THYM." (PMID 37014322, 2023). "To summarize, the study’s results suggest that the abnormal expression of AIF-1 may be linked to the immune response in cancers, which could offer insights for further exploration of the functions and roles of AIF-1 in the onset and progression of cancer." (PMID 37014322, 2023). "Furthermore, ImmuneScore, EstimateScore, StromalScore, and neoantigens were integrated, suggesting that AIF-1 was associated with immune infiltration in some cancers." (PMID 37014322, 2023). "Moreover, gene set enrichment analysis (GSEA) was applied to determine the cancer hallmarks associated with AIF-1 expression." (PMID 37014322, 2023). "A substantial body of research has linked the expression of AIF-1 to cancer progression, metastasis, and prognosis, indicating that AIF-1 could serve as a valuable biomarker and therapeutic target." (PMID 37014322, 2023). "A transcriptomic profile investigation followed by immunohistochemistry validation has identified the allograft inflammatory factor 1 (AIF1) gene as an unfavorable prognostic factor in this carcinoma and demonstrated that it is associated with immune infiltrates." (PMID 35656508, 2022). "Based on our findings that AIF-1 expression is positively correlated with the expression of CD28, CD84, CD86, and LAIRI in several cancer types, we hypothesize that further investigation into the potential association between AIF-1 and these immune regulators would be promising." (PMID 37014322, 2023). "Thus, we explored the mutation landscape of AIF-1 across cancers." (PMID 37014322, 2023). "Nevertheless, this pan-cancer study provides a deeper understanding of the role of AIF-1 in the functional nucleus of different tumors." (PMID 37014322, 2023). "To identify the cancer hallmarks associated with AIF-1 expression, we used differentially expressed genes (DEGs) between low-AIF-1 and high-AIF-1 subgroups in each cancer to conduct GSEA." (PMID 37014322, 2023). "In this study, we extensively examined AIF-1 expression levels in multiple databases, covering a wide range of cancers." (PMID 37014322, 2023). "AIF-1 expression was positively correlated with immune infiltrating cells and immune checkpoint-related genes in most cancers." (PMID 37014322, 2023). "Our findings demonstrated coexpression between AIF-1 and these methyltransferase genes in almost all cancer types except for SKCM, PCPG, MESO, ESCA, DLBC, and ACC." (PMID 37014322, 2023). "Accordingly, we analyzed gene expression and alteration cooccurrence to identify potential functional partners of AIF-1 in various cancer types." (PMID 37014322, 2023). "Materials and Methods: We first analyzed AIF-1 expression across cancers based on data from public databases." (PMID 37014322, 2023).
cancer (continued). "AIF-1 was positively linked with the infiltration levels of CD8+ T cells, Tregs, monocytes, macrophages, and CAFs in most TCGA cancers." (PMID 37014322, 2023). "The findings above indicate that AIF-1 has a crucial role in predicting the prognosis of patients and has the potential to serve as a robust biomarker for predicting certain types of cancer." (PMID 37014322, 2023). "We determined that AIF-1 has the potential as a valuable biomarker in diverse cancers, particularly in the age of immunotherapy." (PMID 37014322, 2023). "Although the importance of AIF-1, its expression profile, prognostic significance, and functional implications in the majority of cancer types have yet to be systematically investigated." (PMID 37014322, 2023). "As such, there is a crucial need to take a fresh and comprehensive approach to examine the involvement of AIF-1 across different cancers." (PMID 37014322, 2023). "Univariate Cox regression and Kaplan-Meier analyses were used to explore the predictive value of AIF-1 expression in various cancers." (PMID 37014322, 2023). "We conducted further analysis to evaluate the connections between AIF-1 and cancer immunity by examining the correlations between AIF-1 expression and infiltration of immune cells." (PMID 37014322, 2023). "In contrast, AIF-1 expression was negatively related to the infiltration levels of MDSCs in most cancers, except for LIHC and THYM." (PMID 37014322, 2023). "Taken together, these results suggest that epigenetic methylation of AIF-1 in cancer patients is connected with dysfunctional T-cell phenotypes through various mechanisms, leading to distinct prognoses." (PMID 37014322, 2023). "A possible reason for this apparent discrepancy is that AIF-1 is mainly expressed in infiltrating macrophages around cancer tissues, whereas TCGA-based analyses considered AIF-1 expression within the cancer tissue itself." (PMID 36520870, 2022). "Taken together, our results indicate that AIF-1 is expressed in macrophages that infiltrate NSCLC tissue and that higher AIF-1 expression is associated with more aggressive behavior of cancer." (PMID 36520870, 2022). "AIF-1 has also been described in different cancer cell lines, where it is responsible for cell proliferation and migration in some cancer patients." (PMID 32708725, 2020). "Considering these findings, caspase-independent cell death (aif1-dependent in this case) activated after camphor exposure can be further investigated in mammalian cancer cells." (PMID 31892813, 2019). "On the other hand, most malignant tumors shift their energy generation metabolism to oxidative glycolysis, which may be hampered by the elevated AIF1 level in mitochondria." (PMID 40806359, 2025). "Indeed, we found that patients with AIF1-high tumors responded significantly better to standard chemo-/radiotherapy or chemotherapy than those with AIF1-low cancers." (PMID 40806359, 2025). "Surprisingly, scientists have discovered the role of AIF1 in regulating cancer in recent years." (PMID 38521928, 2024). "In the network, eight genes related to the apoptotic process and cell migration, including Mmp9, Cxcl12, Cdh1, Fap, Itga6, Mdk, Aif1, and Mif, were downregulated with co-treatment, which may play vital roles in inhibition of cancer progression and cell death." (PMID 36765032, 2023). "AIF-1 reduction dramatically slowed the growth and occurrence of cancers." (PMID 37014322, 2023). "In this pan-cancer study, we investigated various aspects of AIF-1 expression." (PMID 37014322, 2023). "Additionally, we examined the expression of four methyltransferase genes (DNMT 1, 2, 3A, and 3B) in various cancer types and investigated their relationship with AIF-1." (PMID 37014322, 2023). "Taken together, these findings indicate that AIF-1 is prominently upregulated and expressed in most cancers, which strongly implies that AIF-1 may play a crucial role in the initiation and progression of tumorigenesis." (PMID 37014322, 2023).
cancer (continued). "Therefore, the results of our pan-cancer analysis demonstrated that AIF-1 has the potential to be taken as a predictive biomarker for prognosis and immunotherapy response, which needs further investigation." (PMID 37014322, 2023). "Based on our findings, it appears that AIF-1 may be able to serve as a predictor of the efficacy of immune checkpoint inhibitors (ICIs) in the specific types of cancers being studied." (PMID 37014322, 2023). "There was a correlation between the varying methylation statuses of AIF-1 and differential mRNA overexpression levels in those cancer types, indicating that epigenetic methylation of AIF-1 might impact the transcriptome of diverse cancers." (PMID 37014322, 2023). "Additionally, we further investigated the correlation between AIF-1 expression and gene mutations, gene modifications, immune cell infiltration, TMB, and MSI in different cancers." (PMID 37014322, 2023). "Our results revealed that AIF-1 was significantly correlated with the five MMR genes in pan-cancer." (PMID 37014322, 2023). "Consistent results were obtained from the Kaplan-Meier analysis of disease-specific survival (DSS) in KIRC, CESC, and SKCM, suggesting that AIF-1 may be a prognostic biomarker for these cancers." (PMID 37014322, 2023). "YKL-40 gene expression was primarily increased in the fibroblast (gene annotation: COL1A, BGN, DCN), myeloid (gene annotation: CD68, LYZ, AIF1), cancer (gene annotation: EPCAM, KRT7, KRT18), and B-cell (gene annotation: CD79A, CD79B) populations in cancer tissue compared to healthy tissue." (PMID 35631632, 2022). "Our results suggest that metabolic stress-induced cell death in CHTM1-deficient cancer cells is predominantly associated with AIF1 modulation and not cytochrome c or Smac alterations." (PMID 31221176, 2019). "Daintain/AIF1 (allograft inflammatory factor) is a crucial mediator hub of inflammatory response and cell migration, and an overexpression of this protein has been reported to be involved in several cancers." (PMID 30419021, 2018). "Previous studies have reported an increase in AIF1 expression in malignancies and suggest that it may have a significant role in cancer progression." (PMID 30386176, 2018). "Consequently, it is essential to evaluate the role of AIF-1 across various cancer types thoroughly." (PMID 37014322, 2023). "Importantly, our study found that AIF-1 is positively associated with the degree of infiltration of CD8+ T cells, monocytes, and macrophages but negatively associated with the degree of infiltration of dendritic cells and MDSCs in most cancers." (PMID 37014322, 2023). "Hence, these findings indicate that AIF-1 could potentially influence cancer’s progression, prognosis, and treatment through its interaction with immune cells." (PMID 37014322, 2023). "This discovery suggests that AIF-1 may have different functions in different types of cancer." (PMID 37014322, 2023). "Earlier research has demonstrated that epithelial-mesenchymal transition (EMT) is associated with cancer onset, spread, and drug resistance, implying that AIF-1 may have a crucial role in the formation and metastasis of cancer by participating in the EMT process." (PMID 37014322, 2023). "Analysis of cluster-specific genes indicates that these clusters correspond to cancer cells (GFP, Crabp1, Ank), myeloid cells (Aif1, Ctsc, Mpeg1), lymphoid cells (Il2rb, Cd28, Cd3e/g/d, Cd37), and stromal cells (Col1a1/2, Lum, Eln, Dpt), respectively." (PMID 41280683, 2025). "AIF1 is a mitochondrial FAD-dependent oxidoreductase that plays a vital role in oxidative phosphorylation and redox metabolism in normal and cancer cells." (PMID 29340048, 2017). "Like AIF1, PRRX1 expression strong correlated with its interacting partners, several of which were conserved across the four cancers." (PMID 26272668, 2015).
cancer (continued). "In addition, the relationships between AIF-1 expression and DSS in pan-cancer were also investigated." (PMID 37014322, 2023). "In a gallbladder cancer mouse model, the inhibition of AIF1 leads to the decreased secretion of inflammatory factors and cell proliferation, augments cell apoptosis, and limits the invasion and epithelial-mesenchymal transition (EMT) of cancer cells via the TGF-β1/p38 pathway." (PMID 37237507, 2023). "Moreover, AIF-1 correlated with TMB in 12 cancers and MSI in 11 cancers, which suggested that AIF-1 can be used as a new biomarker to predict ICI response for certain cancers." (PMID 37014322, 2023). "AIF-1 has been found to co-localize with CD68+ macrophages in human atherosclerotic coronary arteries, renal interstitium, and synovial membrane, being considered a marker of activated macrophages and endowed with prognostic value for inflammation-related diseases including cancer." (PMID 36520870, 2022). "To confirm that regulation of immunomodulation and metastasis by master regulators AIF1 and PRRX1 were not specific to the TCGA datasets, we independently validated gene interactions regulated by Set 1/Set 1-s and Set 2 for six cancers in in other datasets of six cancers." (PMID 26272668, 2015).
neurological diseases (12 papers, 2014 to 2024). "AIF1 has potential as a biomarker for neuroinflammation and may be a target for therapeutic interventions in neurological disorders." (PMID 38715397, 2024). "Microglia from non-neurological disease controls and individuals with ASD in both the snRNA-seq and scRNA-seq datasets expressed characteristic microglial markers such as P2RY12, CX3CR1, AIF1, CSF1R and IL18." (PMID 35739273, 2022).
kidney (5 papers, 2022 to 2025). "In this study, we first demonstrated that 2 distinct etiologies of kidney injury, kidney transplant rejection and ischemia reperfusion, were both characterized by AIF-1 upregulation in kidney MΦs." (PMID 39836477, 2025).
bacterial infection (4 papers, 2014 to 2025). "In invertebrates, the expression levels of AIF1 in hemocytes increase following bacterial infection or tissue damage." (PMID 41009586, 2025). "In this bivalve, AIF1 expression increases in response to immune challenges such as bacterial infection or tissue damage, particularly in gills and hemocytes, with peak expression observed within 12 h, suggesting a role in the early phases of acute inflammatory responses." (PMID 41009586, 2025). "Notably, a rapid increase in AIF1 expression has been observed in the Pacific oyster following exposure to PAMPs, bacterial infections, or tissue damage, suggesting an active role in the initial stages of acute inflammatory responses." (PMID 41009586, 2025).
metabolic disease (4 papers, 2020 to 2026). A congenital disorder (due to inherited enzyme abnormality) or acquired (due to failure of a metabolically important organ) disorder resulting from an abnormal metabolic process. "Deciphering AIF-1's complex roles in inflammation and metabolic disorders offers critical insights for therapeutic development." (PMID 41694567, 2026).
kidney disease (3 papers, 2023 to 2026). "Thus, therapies inhibiting AIF-1 when ischemic injury is inevitable have the potential to reduce the global burden of kidney disease." (PMID 39836477, 2025).
AIF1 also shares sentences with these, for which no sentence is quoted: depression (53 papers); ischemic stroke (44); amyloid (36); Anxiety (33); Parkinson disease (23); glaucoma (22); Gliosis (21); neurodegenerative disease (21); retinal degeneration (18); Sepsis (17); COVID-19 (16); hematoma (16); cognitive decline (15); epilepsy (15); cerebral infarction (14); viral infection (14); brain injury (10); neuropathy (10); ocular hypertension (9); brain disease (8); Hydrocephalus (8); injury (8); memory impairment (8); histiocytic sarcoma (7); inflammation (7); migraine (7); multiple sclerosis (7); amyotrophic lateral sclerosis (6); psychiatric disorder (6); Senile plaques (6).
A further 212 diseases each share a sentence with AIF1 in 5 papers or fewer.